RAD18 (RAD18 E3 ubiquitin protein ligase)
Diseases named in the same sentence as RAD18 in open-access papers (continued):
Sharing a sentence is not in itself a finding about the gene and the disease.
cancer (continued). "Collectively, our findings identify RAD18 as a potential pan-cancer prognostic biomarker and immunotherapeutic target, with targeting RAD18 holding promise for reversing immunotherapy resistance in solid tumors." (PMID 42115304, 2026). "CHAF1A facilitates PCNA K164 monoubiquitination mediated by RAD18, thereby promoting the recruitment of Y-family DNA polymerases and enhancing cancer cell resistance to DNA damage." (PMID 40025006, 2025). "RAD18 is a key component in the TLS pathway and has been associated with the development of chemoresistance in cancer cells." (PMID 40016217, 2025). "A pan-cancer analysis of RAD18 expression revealed elevated levels in OC tissues compared to normal tissues." (PMID 40016217, 2025). "In a reciprocal manner, M2-polarized TAMs secrete TGF-β to activate RAD18, thus promoting cancer stemness and establishing a feedback loop." (PMID 39286635, 2024). "Our work reveals a previously unappreciated role of the RAD18, UBC13, PALB2 and RNF168 pathway in replication fork recovery in BRCA1-deficient cancer cells." (PMID 38943334, 2024). "In all the MGMT-deficient patient-derived models of cancer (PDMCs) that we investigated, TMZ-tolerance was RAD18-dependent." (PMID 38438348, 2024). "We also show that RAD18 protein levels are elevated in primary and metastatic BRCA1-deficient cancer tissues relative to BRCA wild-type tumors." (PMID 38943334, 2024). "RAD18 is a key factor contributing to increased resistance to radio/chemotherapy in several cancers, therefore it is of high therapeutic interest to inhibit RAD18 in these scenarios." (PMID 38448672, 2024). "Disrupting this loop can suppress cancer stemness, highlighting the critical interplay between RAD18, YAP, and TGF-β in TNBC CSC characteristic." (PMID 39286635, 2024). "The results of our study suggest the positive feedback loop between RAD18 and TAMs plays a vital role in cancer progression, and that it operates through a mutual action between DDR and TAMs." (PMID 35413945, 2022). "Numerous past studies have demonstrated that elevated levels of RAD18 gene expression are related to cancer progression and resistance to ionizing radiation in a number of malignancies." (PMID 35426246, 2022). "RAD18 has recently been discovered to be expressed aberrantly in a variety of malignancies, where it involves in the occurrence and progression of cancer." (PMID 35426246, 2022). "Inhibition of YAP or TGF-β breaks this loop and suppresses cancer stemness and proliferation In nude mice, RAD18 promoted subcutaneous transplanted tumor growth and M2-type TAM recruitment." (PMID 35413945, 2022). "By doing so, RAD18 protects the human genome from damage when it is faced with stresses such as those seen in cancer cells." (PMID 36480547, 2022). "Previous studies have shown that RAD18 is highly expressed in multiple human cancers and that elevated RAD18 expression is related to poor outcome." (PMID 35413945, 2022). "Specifically, the DNA repair genes like RAD51B and RAD18, cancer stem cell marker SOX2 and antiapoptotic genes were significantly up regulated in radiation resistant cells." (PMID 34762666, 2021). "We will particularly focus on the critical actors of these two processes, Rad18 and Polθ, which represent promising targets in cancer therapy." (PMID 33920223, 2021). "MAGE-A4 overexpression stabilizes Rad18 by protecting it from ubiquitin-mediated degradation, allowing for its continued over-activation in cancer cells." (PMID 33023096, 2020). "We also found a significant correlation between IGF1R/PCNA and RAD18/PCNA colocalization in cancer tissue, indicating a possible link to TLS activation." (PMID 32701997, 2020). "As the association of RAD18 with MAGE-A4 provided a potentially important new relationship between DNA-damage tolerance and cancer, we validated and further characterized the RAD18–MAGE-A4 interaction." (PMID 27377895, 2016).
cancer (continued). "Most of our understanding of the mammalian RAD18–TLS signalling pathway stems from studies performed in cultured cancer cell lines." (PMID 27377895, 2016). "Clearly, biophysical and crystallographic studies will be necessary to fully characterize the putative [RAD18]2–RAD6–MAGE-A4 complex that exists in cancer cells." (PMID 27377895, 2016). "Here the authors show that MAGE-A4 stabilizes RAD18 and allows cancer cells to maintain on-going DNA synthesis in the face of genotoxic injury." (PMID 27377895, 2016). "The lack of G2/M checkpoint activation in response to IR exposure due to the depletion of RAD18 was also confirmed in three other human cancer cell lines." (PMID 25675240, 2015). "In accordance with a previous report, we showed that RAD18-depleted human cancer cells have an increased sensitivity to IR." (PMID 25675240, 2015). "In our previous study we demonstrated that disruption of RAD18 abrogates PCNA polyubiquitination in several cancer cell lines after UV irradiation." (PMID 20353596, 2010). "In cancer cells, RAD18 E3 ubiquitin protein ligase (RAD18) plays a key role in DNA damage repair." (PMID 39935428, 2025). "Our data indicate that the role of RAD18 in fork recovery, in addition to its proposed function in ssDNA gap filling, could also be relevant for survival in BRCA1-deficient cancer cells." (PMID 38943334, 2024). "Furthermore, the activation of the Hippo-YAP pathway in TNBC cells, driven by RAD18, stimulates cancer cell proliferation and invasion." (PMID 39286635, 2024). "Accumulating evidence indicates that the expression level of RAD18 contributes to mutagenesis and DNA damage-based cancer therapy resistance, hinting the necessity and significance of understanding the regulatory mechanism governing RAD18 function in maintaining genome stability and tumorigenesis." (PMID 38719812, 2024). "Based on our result that mutation of the major RAD18 O-GlcNAcylation residues sensitizes cell to CPT exposure, it is reasonable to speculate that targeting RAD18 O-GlcNAcylation in cancer cells may have potential therapeutic benefits." (PMID 38719812, 2024). "Inhibiting RAD18-mediated TLS is a potential therapeutic strategy for sensitizing cancer cells to TMZ-induced lethality, yet could also have significant impact on mutagenesis." (PMID 38438348, 2024). "As a result, loss of RAD18 or UBC13 in BRCA1-deficient cancer cells does not abrogate reversed replication fork degradation, which is instead rescued upon knockdown of the fork reversal translocases SMARCAL1, ZRANB3 or HLTF." (PMID 38943334, 2024). "We found that RAD18 knockout significantly diminishes cell viability in BRCA1-deficient but not BRCA1-proficient cancer cells." (PMID 38943334, 2024). "We also aimed to determine whether the RAD18/UBC13-dependent pathway of fork recovery could be targeted to modulate viability and/or drug sensitivity in BRCA1-deficient cancer cells." (PMID 38943334, 2024). "The RAD18-YAP-TGF-β loop is essential for cancer cells to maintain or promote their CSC phenotype and could be a potential therapeutic target for TNBC." (PMID 35413945, 2022). "Rad18 inhibition may, at the same time, reduce cancer fitness by decreasing RS tolerance and increasing endogenous DNA damage such as ssDNA gaps." (PMID 33920223, 2021). "RAD18 mRNA and RAD18 protein are aberrantly overexpressed in many cancer cell lines." (PMID 34663880, 2021). "Thus, targeting either Rad18-mediated TLS or Polθ has the potential to substantially improve clinical outcomes in cancer." (PMID 33920223, 2021). "Interestingly, RAD18 promotes replication fork protection in BRCA1 mutant cancers through the PCNA-TLS pathway." (PMID 32182354, 2020). "MAGE-A4 depletion from MAGE-A4-expressing cancer cells destabilizes RAD18." (PMID 27377895, 2016).
cancer (continued). "However, in a previous study we were the first to demonstrate that K63-linked polyubiquitination is important in human fibroblasts and that PCNA is both mono and polyubiquitinated in cancer cell lines by Rad18 and Ubc13." (PMID 20353596, 2010). "In the present study, we analyzed the expression and the mutation of Rad18 in human cancer cell lines and NSCLC tissues and also assessed whether there is some functional difference due to the SNP of Rad18." (PMID 19630985, 2009). "RT-PCR SSCP of Rad18 in 33 cancer cell lines was analyzed by PCR-SSCP." (PMID 19630985, 2009). "The expression of Rad18 gene in human cancer cell lines was analyzed by RT-PCR." (PMID 19630985, 2009). "Similarly, elevated RAD18 expression is associated with advanced TNBC and poorer prognosis, suggesting that increased DNA repair activity contributes to the aggressiveness of these cancers." (PMID 40362184, 2025). "Therefore, fine-tune of RAD18 function might be a promising approach for sensitizing cancer cells to genotoxic therapeutic agents." (PMID 38719812, 2024). "Moreover, our data highlight that RAD18 is required for PCNA monoubiquitination upon HU treatment as detected by immunoblotting, consistent with our finding that PCNA ubiquitination at the K164 residue promotes fork recovery in BRCA1-deficient cancer cells." (PMID 38943334, 2024). "Indeed, our data show that RAD18 recruitment to chromatin upon HU treatment depends on RFN168 in BRCA1-deficient cancer cells, indicating that RNF168 might act upstream of RAD18 to facilitate its recruitment to degraded forks and fork recovery." (PMID 38943334, 2024). "Furthermore, the MAGEA4/RAD18 interface represents a potential drug target for cancer therapies." (PMID 38448672, 2024). "Indeed, both RFWD3 and RAD18 are aberrantly overexpressed in a broad spectrum of cancers." (PMID 37728310, 2023). "Therefore, aberrant RAD18 activation in cancer might preferentially activate individual Y-family DNA polymerases, contributing to TLS pathway imbalance and mutagenesis." (PMID 34663880, 2021). "Therefore, we determined whether MAGE-A4 contributes to RAD18-dependent TLS pathway activation in cancer cells." (PMID 27377895, 2016). "RAD18 is a key component of the TLS pathway, with numerous studies providing substantial proof of its role in cancer metastasis and chemoresistance." (PMID 40016217, 2025). "A variant of R6BD-based peptide or peptidomimetic with high affinity to the peptide-binding groove (PBG) of MAGEA4 has the potential to be a therapeutic agent in cancers overexpressing MAGEA4 and RAD18." (PMID 38448672, 2024). "RAD18-mediated TLS is also potentially responsible for the spontaneous and acquired resistance of cisplatin therapy in cancer cells." (PMID 38719812, 2024). "Our data provide unique insights into RAD18-driven PCNA monoubiquitination and the regulation of this process by MAGEA4 in cancers." (PMID 38448672, 2024). "In our study, we found that E2F7 was significantly up-regulated in CRC cells, fostered the malignant progression of cancer cells, and hampered the killing effect of NK cells on CRC cells by activating RAD18 transcription." (PMID 38073330, 2024). "To further explore this, we analyzed a pharmacogenomics dataset comprising 1001 human cancer cell lines and examined the correlation between half maximal inhibitory concentration (IC50) values of VE-821 and Rad18 gene expression levels." (PMID 38467834, 2024). "LINC00355 was shown to promote invasion and migration in cancer cells and xenograft animals by regulating the transcription of three downstream genes (ITGA2, RAD18, and UBE3C) and participating in six ceRNA axes." (PMID 38125763, 2023).
cancer (continued). "LINC00355 was shown to promote cancer cell proliferation and tumor growth in xenograft animals by regulating the transcription of three genes (ITGA2, RAD18, and UBE3C) and participating in seven ceRNA axes." (PMID 38125763, 2023). "RAD18 is the E3 ligase that monoubiquitinates PCNA, a central signaling event in TLS and CYLD is a deubiquitinase involved in cancer and required for efficient TLS, as we have previously reported." (PMID 34203408, 2021). "IGF1R kinase inhibition abolished PCNA/RAD18 interaction and PCNA-mono-ubiquitination showing that this mechanism extends to cancer cells." (PMID 32701997, 2020). "Following the observation of an increased IGF1R/PCNA colocalization in clinical tumors, we performed a similar PLA staining for Rad18 and PCNA on a subset of the clinical cancer panel (n = 16)." (PMID 32701997, 2020). "In this report we identify a cancer cell-specific protein, the cancer/testes antigen (CTA) melanoma antigen-A4 (MAGE-A4), as a novel binding partner and stabilizing factor for RAD18." (PMID 27377895, 2016). "Our work identifies RAD18 as a target of MAGE-A4 and provides a new potential mechanism by which genome maintenance and genome stability can be altered in cancer cells." (PMID 27377895, 2016). "However, the status of Rad18 in human cancers is still unknown." (PMID 19630985, 2009). "Therefore, we believe that RAD18 recruitment to the stalled replication fork is performed by a number of proteins, including CHAF1A, to enable cancer cells to rapidly respond to DNA replication stress." (PMID 40025006, 2025). "By promoting the monoubiquitination of proliferating cell nuclear antigen (PCNA), RAD18 activates the Fanconi anemia (FA) pathway and recruits TLS polymerases such as DNA polymerase η (pol η) and DNA polymerase ι (pol ι), enabling cancer cells to continue DNA synthesis in damaged genomes." (PMID 39905312, 2025). "By stabilizing RAD18, MAGEA4 facilitates the recruitment of Y-family DNA polymerases, enabling cells to continue replication under DNA damage conditions and thus supporting cancer cell survival." (PMID 39905312, 2025). "Unlike other DNA repair pathways which are lost in cancer, RAD18 and DNA damage tolerance factors are often retained, supporting their role as fail-safe mechanisms for tumor cell survival." (PMID 36480547, 2022). "Finally, the cancer/ testes antigen MAGE-A4 was reported to interact and stabilize Rad18 to activate TLS." (PMID 33920223, 2021). "In some cancer cells, RAD18 protein overexpression is due to a mis-expressed germ cell protein, the Cancer/Testes Antigen MAGE-A4 which directly binds and stabilizes RAD18." (PMID 34663880, 2021). "Therefore, MAGE-A4 can specifically influence replicative bypass of ultraviolet-induced DNA lesions, further consistent with its novel role in regulating RAD18 levels and TLS activity in cancer cells." (PMID 27377895, 2016). "Remarkably, however, it is unknown whether RAD18 and TLS are differentially regulated in cancer cell lines and untransformed cells." (PMID 27377895, 2016). "Inactivation of the CSN-CRL4A/4BCDT2, RAD18, HLTF pathway reduces cell survival and promote apoptosis, suggesting that PRR may be considered as a potential target for cancer therapy." (PMID 23555860, 2013). "RAD18 is one of the critical molecules responsible for the resistance to chemotherapy and radiotherapy in various cancers, therefore, targeting the RING-SAP interface provides a unique way to inhibit RAD18 and could be employed in combination with the genotoxicity-inducing chemo/radio therapies." (PMID 38448672, 2024). "Given the important role of the RAD6/RAD18 (E2/E3) complex in PCNA ubiquitination and polymerase switching from replicative DNA polymerases to damage tolerant TLS polymerases, there is an unmet need to explore if and how such defects can translate into precision cancer medicine." (PMID 29721165, 2018).
cancer (continued). "Though there was no Rad18 mutation in human cancer cell line and NSCLC tissue examined except PC3, as Rad18 functions as post-replication repair system, we have examined whether there is any difference between wild type Rad18 and Rad18 SNP in vitro." (PMID 19630985, 2009). "Based on the observation that Rad18 is actually highly expressed in 5-FU-resistant CRC cells, miR-145 could play a significant role in debilitating the DNA damage response through its inhibitory effect on Rad18 and counteracting drug resistance in cancer cells." (PMID 33023096, 2020). "Regardless of the mechanism of MAGE-A4–RAD18 interaction, we show here that endogenous MAGE-A4 confers RAD18 stability and expression in cancer cells." (PMID 27377895, 2016). "To investigate roles of RAD18 in cell cycle checkpoint activation after IR exposure, we analyzed the distribution of the cell cycle using flow cytometry in HT1080 human cancer cell line treated with a non-targeted siRNA (si-ctrl)." (PMID 25675240, 2015). "The stabilisation of RAD18 could promote TLS in the absence of DNA damage, promoting mutagenesis and cancer development." (PMID 38448672, 2024). "Aberrant expression of MAGEA4 in cancer cells may encourage PCNA monoubiquitination and the recruitment of error-prone polymerases, even in the absence of DNA damage, through the stabilisation of RAD18." (PMID 38448672, 2024). "As Rad18 interacts with Rad6 and function as a ubiquitin enzyme to activate PCNA, if these key proteins were involved in cancer, the PRR system will not function and might lead to cancer development." (PMID 19630985, 2009).